APOB (apolipoprotein B)
Diseases named in the same sentence as APOB in open-access papers (continued):
Sharing a sentence is not in itself a finding about the gene and the disease.
tumor (continued). "The proposed explanation is that ApoA-I is negatively associated with tumor-induced systemic inflammation, while elevated ApoB indicates a higher systemic inflammatory marker, and so a high ApoB/ApoA-I ratio, which is considered atherogenic, may contribute to tumor necrosis." (PMID 38067270, 2023). "By examining the mutated genes, we found that tumor cells progressively acquired non-synonymous mutations in genes such as KTN1, ALB, APOB, CDK11A, and CDK11B." (PMID 41373592, 2025). "While diverse roles of EV-mediated intercellular communication in the biology of tumor microenvironment have been widely investigated, the respective contribution of APOB-carrying EV for the Warburg phenotype is still poorly understood." (PMID 40089067, 2025). "Beyond signaling molecules, TDEVs can directly transfer glycolytic enzymes and metabolites, such as apolipoprotein B-100 (APOB), to recipient cells, promoting the Warburg effect and sustaining tumor growth under nutrient-limited conditions." (PMID 41459253, 2025). "Combined with the observation that APOB is mutated in about 10% of human HCC and that APOB mutation is associated with decreased survival probability in HCC, this finding highlights a tumor suppressive function of APOB in HCC." (PMID 38302473, 2024). "To assess the potential tumor suppressor role of APOB in HCC, we employed the Spearman correlation coefficient to evaluate the relationship between APOB and CD274, PDCD1, and CTLA4." (PMID 38310202, 2024). "Overall, 97.4% of CRCs with tumor sizes of 3-5 cm and 82.1% of those with tumor sizes >5 cm demonstrated high apoB expression." (PMID 36864816, 2023). "Although apoB has been linked to CRC development, little is known about its involvement in modulating CRC oncogenic or tumor-suppressor signaling." (PMID 36864816, 2023). "Another limitation was a lack of mechanistic studies to determine the significance of high apoB expression and low 4HNE expression in certain tumor sites and sizes." (PMID 36864816, 2023). "Plasma lipids were similar between controls (CTR) and all women with BC, but when categorized according to tumor molecular type, triple-negative (TN) BC cases had higher plasma TC, TG, and apoB values compared to other molecular types." (PMID 37268673, 2023). "Higher serum concentrations of TG and ApoB and lower HDL-C levels were recorded in tumor ε4 allele carriers among the southern China population in the present study; these findings are consistent with those of our past research studies." (PMID 36057714, 2022). "In the present study, we screened circulatory samples from 231 CRC patients with or without metastasis for the lipid metabolism parameters along with the IHC staining for apoB in the tumor tissues." (PMID 36713523, 2022). "Then we performed the immunohistochemistry staining of APOB in a CCA tumor microarray which contained 100 CCA cases, APOB was down-regulated in CCA samples." (PMID 33954113, 2021). "Since knockdown of HNF4A caused a reduction in ApoB and HNF1A expression, possibly loss of HNF4 reduces the expression of these genes and subsequently tumor growth is triggered." (PMID 29899848, 2018). "Recently, it has been uncovered that APOBEC (apolipoprotein B mRNA editing enzyme catalytic polypeptide) family members are endogenous drivers of tumour diversity in many tumour types." (PMID 28716075, 2017). "Increased APOB/APOA1 ratio significantly associated with nodal metastases (P = 0.010), high tumor necrosis percentage (P = 0.041), and decreased APOB/APOA1 ratio with cholesterol-lowering medication (P = 0.015)." (PMID 28710487, 2017).
tumor (continued). "Although the exact mechanisms remain unclear, this study confirms that SA1 can inhibit tumor progression by modulating APOB-related lipid metabolism processes, indicating that APOB is a promising new target worthy of further investigation." (PMID 41011152, 2025). "Further research indicates that APOB may regulate metastasis indirectly through tumor microenvironment pathways, including TGF-β, T-cell receptor, and leukocyte transendothelial migration." (PMID 41291156, 2025). "CXCL9 enhances immune surveillance and promotes the killing of tumor cells, while the negative correlation between APOB and CXCL9 may imply a potential role of APOB in tumor immune evasion." (PMID 40696350, 2025). "Moreover, signatures 2 and 13, which are related to the apolipoprotein B mRNA-editing enzyme catalytic polypeptide, were found in tumor samples from patient S431." (PMID 41301905, 2025). "Augmented APOA1 reflects its potential role in driving therapeutic resistance and disease progression by reprogramming the lipid metabolic network of tumor cells; APOB, APOC3, and APOH may function like APOA1." (PMID 39318189, 2024). "Specifically, remnant cholesterol particles can promote inflammation and oxidative stress in the colorectal tissue microenvironment, while elevated APOB levels may reflect broader metabolic dysregulation that creates conditions favorable for tumor development." (PMID 39857597, 2024). "APOB has recently been reported to play a role as tumor suppressor protein." (PMID 38283944, 2023). "However, we also found that tumors with a size of 3-5 cm were more likely to have a high apoB expression than tumors larger than 5 cm, which indicates that the tumor requires apoB at later stages of progression." (PMID 36864816, 2023). "As APOB synthesis and secretion require abundant energy, tumor cells may conserve energy for their proliferation by inactivating the APOB gene." (PMID 38067270, 2023). "The differences in apoB and 4HNE expressions in different tumor sites and sizes may indicate a role of these proteins in CRC development." (PMID 36864816, 2023). "In contrast, the APOBEC (apolipoprotein B mRNA editing enzyme, catalytic polypeptide-like) mutational signature, which is one of the most prominent COSMIC mutation signature in neoplasms due to it affecting the tumor immune-escape, is enriched later in NSCLC than in other solid tumors." (PMID 35406585, 2022). "Oppositely, apoB is responsible for cholesterol accumulation in peripheral tissue and tumor cells." (PMID 34979995, 2022). "Moreover, the IHC verification for apoB in the CRC tissue provided a preliminary result for the relationship between tumor and circulation." (PMID 36713523, 2022). "Specifically, a non-oncogenetic mutation of APOB is observed, which can cause APOB inactivation and is correlated with overexpression of oncogenic regulators and downregulation of tumor suppressors, leading to worse outcomes of survival." (PMID 36506554, 2022). "Distinctive from ApoC1, ApoB and ApoA1 seem to be tumor suppressors in RCC." (PMID 36506554, 2022). "As for the antitumour activity, in comparison to free DOX, ApoB/DOX-NLC promoted lower tumour volume, decreased mortality without body loss (in relation to naïve animals), and no cardiac tissue damage after ex vivo analysis." (PMID 34834022, 2021). "Additionally, APOB could suppress tumor immune cells through the reduction of immune checkpoint infiltration and expression." (PMID 38310202, 2024). "Moreover, recombinant apoB could be used as a carrier of anti-tumor drugs, such as chemotherapy agents and small interfering RNA targeting oncogenes." (PMID 34979995, 2022).
tumor (continued). "Different from ApoA1 and ApoM, a high ApoB level may be a risk factor for HCC as it is correlated with poorer post-surgery survival in HCC patients, and individuals with higher ApoB level tend to have a larger tumor size." (PMID 36506554, 2022). "From the TCGA database of CCA, we found that the tumor tissues showed higher DNA methylation levels when compared to their normal liver tissue at the sites cg0763176, cg15246511, and cg26112457, and cg05606082 - which were the target sites of the APOB CpG island." (PMID 33954113, 2021). "APOB ablation is significantly associated with poor clinical outcome in patients with HCC and increased proliferation of HCC cells, indicating that APOB may have weak tumor suppressive activity." (PMID 30429453, 2018). "We also assessed the protein expression of ANPEP, APOB, and GLP1R in tissues from the primary, tumor, and metastatic groups using IHC staining." (PMID 40696350, 2025). "Specifically, a non-oncogenetic mutation of apolipoprotein B is observed, which can result in apolipoprotein B inactivation and is associated with the overexpression of oncogenic regulators and the downregulation of tumour suppressors, resulting in poorer survival outcomes." (PMID 38263244, 2024). "Attention should be paid to the APOB gene, which is able to impair DNA repair and regulate oncogenic and metastatic regulators (mTOR and PI3K pathways), as well as inhibit tumor suppressors." (PMID 36864816, 2023). "Cycling hypoxia was also shown to promote replication catastrophe in tumor cells and enhance the expression and activity of APOBEC3B (apolipoprotein B mRNA-editing catalytic polypeptide) deaminase, which is involved in tumor mutagenesis." (PMID 36831579, 2023). "Additionally, when taking the IHC results into consideration, high expression of apoB in the CRC tumor tissue might indicate the possibility of liver metastasis, and this request for liver-specific surveillance during the following follow-up for patients who had this characteristic." (PMID 36713523, 2022). "However, tumor cells can regulate molecular processes and shut down virus transcription via epigenetic modification of either the host genome or the viral genome and by the expression of antiviral proteins such as the apolipoprotein B mRNA-editing enzyme (APOBEC)." (PMID 34696274, 2021). "In order to further evaluated the correlation between the APOB and clinical characteristics, then we performed the immunohistochemistry staining of APOB in a CCA tumor microarray (TMA), which contained 100 CCA cases from our center." (PMID 33954113, 2021). "In the validation cohort, univariate analysis showed that the tumor grade, CEA, CA19-9, ApoA-I, ApoB, LDL-C/HDL-C and ApoB/ApoA-I were prognostic of OS." (PMID 31956353, 2020). "In the PSM cohort, univariate analysis showed that the ECOG PS score, primary tumor site, tumor grade, tumor resection, CEA, CA19-9, HDL-C, LDL-C, LDL-C/HDL-C and ApoB/ApoA-I were prognostic of OS." (PMID 31956353, 2020). "Except for APOB and ERBB2, the remaining genes were the target genes selected above, which were highly related to tumor purity, TME score, immune score, and stromal score." (PMID 33014013, 2020). "The tumor grade, CEA, CA19-9, LDL-C/HDL-C and ApoB/ApoA-I were prognostic of OS in all three cohorts." (PMID 31956353, 2020). "In the training cohort, univariate analysis showed that the primary tumor site, tumor grade, tumor resection, CEA, CA19-9, cholesterols, triglycerides, HDL-C, LDL-C, LDL-C/HDL-C and ApoB/ApoA-I were prognostic of OS." (PMID 31956353, 2020). "In the PSM cohort, baseline variables, including age, gender, ECOG PS score, primary tumor site, tumor grade, number of metastatic organs, surgery, chemotherapy, CEA and CA19-9, were well balanced in the high ApoB/ApoA-I group and the low ApoB/ApoA-I group." (PMID 31956353, 2020). "In univariate analyse, Age, TNM stage, tumor stage, node stage, distant metastases, LDH, GGT, TBA, ALP, ALB, ApoB, Fbg were related to OS." (PMID 30909980, 2019).
tumor (continued). "The common prognostic genes between AS event and genes included KRT222, LENG8, APOB, SLC3A1, SCD5, AQP1, and ADRA1A, which played roles in tumor biology." (PMID 31140607, 2019). "The variables age, TNM stage, tumor size, treatment, SLR, APOAI, APOB, ALP, GGT and LDH were identified as predictors of OS in the univariate analysis and were entered into the Cox’s proportional hazards regression." (PMID 29728103, 2018). "The final model included age, tumor size, TNM stage, treatment, apolipoprotein A-I, apolipoprotein B, glutamyl transpeptidase and lactate dehydrogenase." (PMID 29728103, 2018). "The factors in our final model included age, TNM stage, tumor size, treatment, APOAI, APOB, GGT and LDH, and the AIC of the final model was 559.41." (PMID 29728103, 2018). "This study demonstrates novel data on the relationships between tumor characteristics in CRC and serum APOA1 and APOB levels and APOB/APOA1 ratio." (PMID 28710487, 2017). "In both, healthy and tumour samples, the ApoB‐FITC signal was absent until F18, peaking in F24, indicating that the EV‐fractions F16‐F17 are almost lipoprotein‐free (green or blue line)." (PMID 39441012, 2024). "Different apoB and 4HNE levels in CRC may indicate that both markers are differently regulated throughout tumor growth." (PMID 36864816, 2023). "The increase of APOB expression may promote the interaction between DCN and COL1A1, so as to promote tumor metastasis." (PMID 36428687, 2022). "Though relative reports were not as many as apoAI, apoB is considered to have tumor-promoting effects." (PMID 34979995, 2022). "As the results shown, tumor immune response involved pathways, such as TGF-β signaling pathway, T cell receptor signaling pathway, and leukocyte trans-endothelial migration pathway were changed followed by the differential expression of APOB in CCA." (PMID 33954113, 2021). "By comparing with the normal group, we found that apolipoprotein B (APOB) and carbonic anhydrase 1 (CA1) were significantly up-regulated, whereas angiopoietin like 5 (ANGPTL5) and shisa family member 7 (SHISA7) were down-regulated in the tumor samples." (PMID 33050883, 2020). "Instead, serum APOB levels or APOB/APOA1 ratio did not significantly associate with tumor stage, suggesting that tumor progression has less impact on these parameters." (PMID 28710487, 2017). "In conclusion, low serum APOA1 levels are associated with advanced stage and systemic inflammation, while serum APOB does not significantly correlate with tumor stage." (PMID 28710487, 2017). "We demonstrated that low serum APOA1 levels associated with advanced T-class and TNM-stage but low serum APOB levels did not significantly correlate with tumor characteristics." (PMID 28710487, 2017). "Recent data have shed light on a distinct lipid profile in TNBC, indicating elevated plasma levels of triglycerides (TG), total cholesterol (TC), non-HDL cholesterol (nonHDLc), and apolipoprotein B (apo B), suggesting a potential contribution to lipid channeling into the tumor microenvironment." (PMID 39195217, 2024). "Moreover, ApoB, the main structural protein of LDL-C, can promote lipoproteins to enter the blood vessel wall, stimulate the phagocytosis of macrophages, thereby enhancing the inflammatory response to further promote tumor progression." (PMID 35086516, 2022). "However, the apoB expression levels in the CRC tumor were not parallel to the circulating lipid metabolism parameters." (PMID 36713523, 2022). "Additionally, among downregulated hub genes, the expression of acyl-CoA oxidase 1 (ACOX1), apolipoprotein A2 (APOA2), apolipoprotein B (APOB), fibrinogen alpha chain (FGA), and fibrinogen gamma chain (FGG) were negatively correlated with the tumor stage of CCA patients." (PMID 35326644, 2022).
tumor (continued). "Our observation revealed a correlation between decreased APOB levels and unfavorable OS and RFS in HCC patients, irrespective of tumor grade, stage, gender, vascular invasion, AJCC stage T, race, alcohol consumption, and hepatitis virus." (PMID 38310202, 2024). "In vivo, in an orthotopic breast cancer model (induced with 4T1 cells), biodistribution showed that ApoB/DOX-NLC nanoparticles, different than free DOX, promoted drug accumulation in the tumour without any significant deposition in the heart." (PMID 34834022, 2021). "PC patients presented a serum lipids difference from non-PC tumor patients in triglyceride (P=0.001), cholesterol (P=0.005), HDL (P<0.001), LDL (P=0.003), apolipoprotein A1 (P=0.001), apolipoprotein B (P=0.007), and apolipoprotein E (P<0.001)." (PMID 34335950, 2021). "The expressions of APOB, FGA, FGG, APOA1, and F2 were significantly down-regulated in the TCGA-LIHC cohort (P<0.05), but SERPINC1 levels were not significantly different between normal and tumor tissues (P>0.05)." (PMID 33834191, 2021).